XPO1 (exportin 1)
Diseases named in the same sentence as XPO1 in open-access papers (continued):
Sharing a sentence is not in itself a finding about the gene and the disease.
tumor (continued). "We thus identify XPO1 as a bona fide tumor antigen recognized by NK cells that offers an opportunity for a personalized approach to NK cell therapy for solid tumors." (PMID 39178254, 2024). "XPO1, a critical component of nuclear‐cytoplasmic transport, plays a pivotal role in tumour development and therapeutic resistance." (PMID 38783482, 2024). "XPO1 promotes tumor development as a poor prognostic factor in a variety of tumors and is a therapeutic target for screening inhibitors." (PMID 39177040, 2024). "By exporting oncoprotein mRNA complexes with eukaryotic translation initiation factor 4E (eIF4e) out of the nucleus, XPO1 contributes to the elevation of oncoprotein levels, fostering tumor growth and survival." (PMID 38927948, 2024). "KPT-335 (Verdinexor) is a novel SINE that potently inhibits the nucleoprotein Exportin 1 (XPO1/CRM1) of tumor cell lines and reduces the replication level of the influenza virus." (PMID 39132444, 2024). "Collectively, these findings suggest that the XPO1+Epithelial, with TP-TME risk subtype-related features, can serve as a predictor of tumor malignancy." (PMID 39712016, 2024). "Aberrant activation and alteration of XPO1 directly regulate tumor progression, metastasis, and drug resistance in various human malignancies." (PMID 38336745, 2024). "After short-term treatment, the histology of the remaining tumor cells appears both necrotic and with decreased nuclear to cytoplasmic ratio, further corroborating the effect of Xpo1 inhibition on tumor fitness." (PMID 38302473, 2024). "XPO1 not only regulates tumor proliferation but also enhances sorafenib resistance by promoting EMT." (PMID 39712016, 2024). "The results indicate that XPO1 mRNA levels were significantly upregulated in tumor samples compared to normal samples, which was consistent with the paired results." (PMID 39177040, 2024). "Exportin 1 (XPO1) is responsible for the nuclear export of several proteins and RNA species, mainly tumor suppressors." (PMID 38653804, 2024). "XPO1 is a nuclear transport receptor protein responsible for the nuclear export of some growth regulators and tumour suppressors." (PMID 38200019, 2024). "Taken together, these findings highlight the critical role of XPO1-mediated nuclear to cytoplasmic transport in promoting MYC-driven tumor growth." (PMID 38302473, 2024). "Using qRT-PCR analyses further showed increased expression of Xpo1, Rpl12, Rps16, and Eif4a1 in RNA samples from primary prostate and lung metastatic tumor cells of TripleTg mice in comparison to those from PCa tissues of DoubleTg mice." (PMID 38336745, 2024). "Here, the authors show that co-activation of HGF/MET and Wnt/β-catenin signaling in mouse prostates results in DNPC-like tumor lesions with elevated expression of XPO1 and ribosomal proteins." (PMID 38336745, 2024). "Inhibition of XPO1 promotes the nuclear accumulation of TSPs and oncogenes and promotes the apoptosis of tumour cells." (PMID 38783482, 2024). "Our first-in-class inhibitor of HSP110 shows significant potential as a treatment against PMBL and cHL tumor growth when used alone or in combination with an XPO1 inhibitor." (PMID 38773631, 2024). "Multiple SP1 binding sites were identified within the promoter region of the Xpo1 gene and, through these sites, SP1 can regulate Xpo1/Crm1 transcription in transformed tumor cells." (PMID 38336745, 2024). "In conclusion, we utilized high-throughput drug screening data to predict the TNBC patient tumor’s response to hundreds of compounds and identified XPO1 inhibitors as preferentially sensitive in these patients." (PMID 39682167, 2024). "A significant inhibitory effect of Selinexor on AR-dependent and -independent PCa tumor growth was observed both in vivo and ex vivo, suggesting that XPO1 blockade can repress both AR and other oncogenic pathway-mediated PCa growth." (PMID 38336745, 2024).
tumor (continued). "XPO1 is the main mediator of nucleocytoplasmic transport and is overexpressed in a variety of human malignancies and closely related to tumour occurrence and development." (PMID 38200019, 2024). "Exportin 1 (XPO1) is one of the major players in protein transport in the nucleus, and recently it is also observed that XPO1 alteration plays a vital role in tumor pathogenesis." (PMID 37047788, 2023). "Immunohistochemical assessment of the tumor tissues showed a significantly reduced expression of proliferation (Ki67) and XPO1 markers following combination therapy compared to the control group." (PMID 37715291, 2023). "Nowadays, it is well-established that the export of proteins, primarily mediated by the karyopherin XPO1, has a profound effect on tumor progression." (PMID 37500615, 2023). "Blocking XPO1 by Sel is bound to have a broad impact on nuclear retention‐mediated signalling in tumour and stromal cell compartments." (PMID 38131168, 2023). "XPO1 is a key nuclear export protein that regulates the nucleocytoplasmic trafficking of a growing number of tumor suppressor proteins, growth regulatory proteins, and chemotherapeutic agents." (PMID 37422534, 2023). "In normal cells, tumor suppressors function in the nucleus, but in tumor cells, XPO1 is overexpressed and transports tumor suppressors out of the nucleus, thereby promoting tumor progression." (PMID 36200270, 2023). "XPO1 is responsible for transporting most of the tumor suppressors and growth regulators; up to 220 proteins bearing the nuclear export signal (a leucine-rich region) are recognized by XPO1." (PMID 36180918, 2022). "While DNA damaging agents transiently activate multiple TPS, high levels of XPO1 in tumors lead to rapid nuclear export of these proteins, extinguishing their tumor suppressor function." (PMID 34562230, 2022). "Improved progression-free survival, overall survival, clinical benefit, stabilization, and control of disease support the novel approach of inhibiting XPO1 for the treatment of these and potentially other tumor entities." (PMID 36140245, 2022). "XPO1 has emerged as a possible anticancer treatment target due to its high expression in tumor cells." (PMID 36110547, 2022). "Selinexor was shown to significantly inhibit tumor growth in preclinical models by selectively blocking XPO1-mediated nuclear export leading to nuclear retention and functional activation of TSP and hindering DNA damage repair (DDR) mechanisms." (PMID 34562230, 2022). "The impaired export of tumor suppressors through SINEs is believed to be one of many potential mechanisms of action for XPO1 inhibitors." (PMID 36140245, 2022). "DNA damage by cytotoxic chemotherapies transiently activate multiple TSPs, high levels of XPO1 in tumors lead to rapid nuclear export of these proteins, extinguishing their tumor suppressor function." (PMID 34562230, 2022). "Leptomycin B specifically recognizes and blocks XPO1 and inhibits cells growth in different tumor cell lines; unfortunately, its strong toxicity limits its clinical application." (PMID 36180918, 2022).
tumor (continued). "Emerging data has suggested that tumor cells overexpress Exportin-1 (XPO1), which is the major nuclear export protein in the cell mediating the efflux of tumor suppressor proteins and the methyl-guanine capped mRNA binding protein eIF4E." (PMID 34562230, 2022). "Another synthetic XPO1 inhibitor is (R)-4'-methylklavuzon, which can retain tumour suppressor proteins in the nucleus by inhibiting the XPO1 protein." (PMID 38938904, 2022). "As shown for various tumor entities, inhibition of the karyopherin exportin-1 (XPO1), a nuclear transport receptor interacting with the leucine-rich nuclear export signal (NES), can have a profound effect on the survival of tumor cells." (PMID 36140245, 2022). "IHC staining of tumor tissue showed that expression of the XPO1 protein was dramatically reduced in the KPT-330 treatment group." (PMID 36180918, 2022). "Drugs in selective inhibitors of nuclear export (SINE) family, such as selinexor and verdinexor, showed effectiveness in blocking XPO1 and maintaining the proper localization of anti-tumor proteins." (PMID 34001144, 2021). "XPO1 transports ribosomal subunits from the nucleus to the cytoplasm and in accordance with this, selinexor inhibits protein translation selectively in tumor cells with upregulated XPO1 expression." (PMID 34926302, 2021). "The inherent complexity of the mechanism behind XPO1 inhibition involves the ability of XPO1 to interact with major tumor suppressors and cell cycle regulators, potentially targeting multiple pathways." (PMID 34504648, 2021). "In DDLPS animal models, selinexor and doxorubicin as single agents induced a tumor growth delay which was more pronounced for the XPO1 inhibitor than the anthracycline in all PDXs (maximum TVI%: 46–80 % vs. 37–60 %)." (PMID 33648535, 2021). "XPO1 transcript and protein were overexpressed in the majority of canine OS tumours and cell lines as compared with normal canine osteoblast cells." (PMID 33438820, 2021). "In summary, XPO1 is a relevant target for therapeutic intervention in canine OS as XPO1 is overexpressed in canine OS tumours and cell lines." (PMID 33438820, 2021). "In conclusion, we identify a novel anti-tumor mechanism for XPO1 inhibitors via HLA-E downregulation and resultant activation of NKG2A+ NK cells." (PMID 34926302, 2021). "XPO1 is overexpressed in the majority primary OS tumours at the RNA and protein level when compared with normal canine osteoblasts." (PMID 33438820, 2021). "Canine OS cell lines and a subset of primary OS tumours showed increased XPO1 transcript and protein expression as compared with normal canine osteoblast cells." (PMID 33438820, 2021). "XPO1 mediates the nuclear export of cellular proteins and is a therapeutic target in many tumor types." (PMID 34439872, 2021). "Immunohistochemical staining of tumor tissues showed that the expression of XPO1 protein in the treatment group was significantly reduced." (PMID 34384466, 2021). "Reports exploring the relationship between SINE efficacy and tumor models with E571K XPO1 have been discussed previously, suggesting a slight reduction in SINE efficacy in PMBCL cell lines (MedB1) and an increase in SINE efficacy in CLL cell lines (NALM-6)." (PMID 33451349, 2021). "Selinexor is a slowly reversible inhibitor of XPO1 with proven preclinical activity in a variety of AML tumor cells." (PMID 32545904, 2020). "Exportin-1, a transporter protein, is responsible for shuttling of many tumor suppressors from the nucleus to the cytoplasm." (PMID 32825184, 2020).
tumor (continued). "Studies with Selinexor and other SINEs provide further novel insights on XPO1’s effects in tumor cells." (PMID 32624581, 2020). "Combined ERα and XPO1 targeting inhibited activation of cell survival mechanisms to provide sustained tumor regression." (PMID 32847042, 2020). "XPO1 (Exportin-1) has been recognized as a potential therapeutic target in multiple tumor types, including AML, and the magnitude of its overexpression at an mRNA and protein level has been directly correlated with poor overall survival." (PMID 32545904, 2020). "Since increased expression of XPO1 has been related to resistance to chemotherapy and worse prognosis in different neoplasias, we studied the potential relationship between expression of XPO1 and sensitivity to selinexor in DLBCL cell lines." (PMID 32691208, 2020). "XPO1 overexpression is commonly observed in solid cancers and haematological malignancies, leading to the aberrant localisations of tumour suppressors and cell cycle regulators, and to enhanced expressions of oncogenes associated with poor prognoses." (PMID 33007990, 2020). "XPO1 exhibited a copy number gain in LUAD tumor tissues, and we observed a significant positive correlation between the XPO1 gene copy number and circXPO1 expression level (r = 0.515, P = 0.017 for Spearman correlation)." (PMID 33268793, 2020). "XPO1 mediates the translocation of several types of RNAs, ribonucleoprotein complexes and more than 200 cargoes, including tumour suppressors and regulatory proteins." (PMID 33007990, 2020). "Exportin 1 (XPO1) is a critical mediator of nuclear export responsible for shuttling more than 200 known cargo proteins including tumor suppressor, anti-inflammatory, and growth-regulating proteins from the nucleus to the cytoplasm." (PMID 30621224, 2019). "More specifically, chromosomal region 2p15‐16 (XPO1/REL) was gained in a higher proportion of tumor cells than the 2p24 region (MYCN) in eight of the 48 patients (17%)." (PMID 31066214, 2019). "We found a reduction of XPO1 protein as early as 24 h, but was more prominently seen at 48 and 72 h, which is aligned to studies published in other distinct tumor models." (PMID 31569391, 2019). "Studies from our group and others have established the utility of targeting XPO1 in several tumor types using selective inhibitors of nuclear export (SINE) compounds." (PMID 31569391, 2019). "In this study we identified a high tendency of XPO1 overexpression towards the moderate/poorly differentiated tumors as well as increase of XPO1 overexpression frequency in advance tumor stages III-IV with significant difference." (PMID 31870117, 2019). "Studies have shown that targeted inhibition of XPO1 by selective inhibitors of nuclear export (SINE) compounds can restore the nuclear TSP function leading to inhibition of tumor growth." (PMID 31905765, 2019). "Previous reports have shown that the specific inhibition of XPO1 suppresses tumor growth and represents a novel target for anticancer therapy." (PMID 30992462, 2019). "Accordingly, in the present study, we tried to address the differences between the overexpression of XPO1 in CRC tumor cells and adjacent normal epithelium." (PMID 31870117, 2019). "Noticeably, the mRNA expression levels of CSE1L and XPOT/6 were highest in tumor pathological grade 4, while the highest mRNA expression levels of XPO1/4/5/7 were found in grade 3." (PMID 31371628, 2019). "XPO1 is highly expressed in many tumor types and coordinates the nucleo-cytoplasmic export of ~220 proteins." (PMID 30115935, 2018). "Previous studies have demonstrated that targeting XPO1-mediated nuclear export, which is often augmented in malignancies, is an effective strategy to limit tumor cell growth." (PMID 30349650, 2018).
tumor (continued). "Overexpression of XPO1 is common in other tumor types and real-time quantitative RT-PCR analysis revealed highly variable mRNA expression levels, suggesting a possibility of XPO1 overactivity also in SI-NETs." (PMID 30045709, 2018). "Further, these authors showed a direct correlation between high XPO1 expression and tumor size, lymphadenopathy and liver metastasis." (PMID 29735942, 2018). "Chromosome region maintenance-1 (CRM1), also known as exportin 1 (XPO1), is a nuclear export chaperone that mediates the export of proteins essential to growth regulation and tumor suppression." (PMID 29765539, 2018). "XPO1 protein levels were assessed in 4 MIBC tumor derived cell lines (T24, TCCSUP, J82, and UM-UC-3) and in a non-transformed but immortalized bladder epithelial cell line (SV-HUC1) by immunofluorescence (IF) and western blot analyses." (PMID 30349650, 2018). "Inhibition of XPO1 results in sequestration of inflammatory mediators and tumor suppressor genes in the nucleus of oncogenic cells, where they exert their effects." (PMID 30332435, 2018). "Western immunoblot analyses of tumor tissue extracts indicate that drug treatment reduced XPO1 expression." (PMID 30349650, 2018). "Previous studies have reported that selinexor interacts with XPO1, which results in a reduction of XPO1 levels and in tumor cell viability." (PMID 30349650, 2018). "CRM1/XPO1 (CRM1) is a nuclear export chaperone that mediates the export of proteins essential to growth regulation and tumor suppression." (PMID 29765539, 2018). "The inherent complexity of the mechanism behind XPO1 inhibition involves the ability of XPO1 to interact with several different tumor suppressors and cell cycle regulators, therefore potentially targeting multiple pathways." (PMID 28810913, 2017). "XPO1 compartmentalizes tumor suppressors and cell cycle regulators, which are dependent on location to exert their apoptotic/proliferative functions." (PMID 28810913, 2017). "Future studies are planned to measure XPO1 occupancy in patient tumor cells to investigate the correlation between the preclinical results described here to clinical occupancy and drug response in patients." (PMID 29299164, 2017). "This study demonstrates that the tumor cell‐specific 3D nuclear telomere organization is sensitive to XPO1 inhibition." (PMID 26991404, 2016). "In this study we found that XPO1 inhibition preferentially affects tumor cells by disrupting their 3D nuclear telomere organization, while normal cells are minimally affected." (PMID 26991404, 2016). "In univariate analysis (Wald test), XPO1-based group (p=7.5E-06), pathological tumor type (p=4.30E-05), and CINSARC class (p=1.6E-11) were associated with MFS." (PMID 27487856, 2016). "The in vitro study of XPO1 inhibition suggested a preference of XPO1‐inhibition‐mediated 3D nuclear telomere disruption in tumor cell lines." (PMID 26991404, 2016). "In future studies it is important to test the effect of selinexor on slow growing tumors, the roles of specific XPO1 cargos, and to study the impact of the selinexor-induced senescent cell population on long-term tumor-level response and re-lapse." (PMID 26399741, 2015).